CD44 (CD44 molecule (IN blood group))
Diseases named in the same sentence as CD44 in open-access papers (continued):
Sharing a sentence is not in itself a finding about the gene and the disease.
colorectal cancer (continued). "The knock-down of CD44 or inhibitory antibody of CD44 attenuated OPN secretion preventing OPN-activated c-jun-NH2-kinase signaling resulting in a decrease in clonogenicity of colorectal cancer cells." (PMID 29747682, 2018). "LncRNA GAPLINC, a newly identified functional LncRNA, also known as a positive CD44 Regulator, was recently described in patients with gastric and colorectal cancer." (PMID 29692777, 2018). "CD44+/CD133+-associated multidrug resistance is reversed by miR-139-5p, with a reduction in Notch1 in colorectal carcinoma cells." (PMID 30470250, 2018). "Xenograft tumors originated from EpCAM+/CD44+ colorectal cancer cells maintain a differentiated phenotype and are able to reproduce the full morphologic heterogeneity of their parental tissue." (PMID 29064439, 2017). "Recent studies demonstrated that CD44+/CD24+ colorectal cancer cells show greater clonogenic potential in vitro and tumor initiation in vivo." (PMID 28030837, 2017). "We have previously demonstrated that ONC201 downregulated CSC markers CD133, ALDH1A1 and CD44 in colorectal cancer cells in vitro and in vivo." (PMID 28767654, 2017). "Recent studies in breast and colorectal cancer demonstrated that inhibition of the SUMO pathway repressed CD44 and cleared the CSC population, mediated through SUMO-unconjugated TFAP2A." (PMID 29383121, 2017). "Because CD44+/CD166+ double-positive cells are more tumorigenic than CD44+ single-positive cells in colorectal cancers, CD166 is an attractive marker for the further enrichment of CD44+ CSCs." (PMID 29064439, 2017). "Colorectal cancer stem cells (CSCs) are responsible for the initiation, progression and metastasis of human colorectal cancers, and have been characterized by the expression of cell surface markers, such as CD44, CD133, CD166 and LGR5." (PMID 29064439, 2017). "Inhibition of the SUMO pathway in basal breast and colorectal cancers repressed CD44 expression, which was dependent upon TFAP2A." (PMID 29383121, 2017). "CD44 has been used as a marker to isolate CSCs from various types of solid tumors such as breast, pancreatic, prostate and colorectal cancers." (PMID 29064439, 2017). "In agreement, we find that FUT9 silencing decreases the expression of the colorectal cancer TIC marker CD44 and the level of the OCT4 transcription factor, which is known to support cancer stemness." (PMID 29196508, 2017). "By separating CD44+/CD133+ cancer stem cells from parental HCT8 human colorectal cancer cells, we found a significantly higher level of autophagy in the CD44+/CD133+ cells than in the parental cells." (PMID 27129175, 2016). "In conclusion, enhanced autophagy activity was observed in the CD44+/CD133+ CSCs purified from the HCT8 human colorectal cancer cell line." (PMID 27129175, 2016). "Using the HCT8 human colorectal cancer cell line, we isolated and purified CD44+/CD133+ CSCs from parental cells and then compared the autophagy and radio-sensitivity between cells." (PMID 27129175, 2016). "Next, the mRNA expression of several important β-catenin target genes, including c-myc, cyclin D1, and CD44, was examined by Q-PCR in breast and colorectal cancer cells." (PMID 27779255, 2016). "We therefore performed FACS analysis to quantify the percentage of the CD44+ cell population in both hypoxic and normoxic colorectal-cancer cells." (PMID 26965643, 2016). "Because CSCs have been found to be resistant to radiation, we tried to uncover the role of autophagy in radio-resistance by purifying the CD44+/CD133+ CSCs from the HCT8 human colorectal cancer cell line." (PMID 27129175, 2016). "Different methods have been used to identify the CSCs in colorectal cancer, and the isolated subpopulation of CD44+/CD133+ cells from human colorectal cancer has been confirmed to be characterized as CSCs." (PMID 27129175, 2016). "We measured CD133, CD44 and Oct4 expression by flow cytometry and investigated the fluorescent intensity of B7-H3 staining in colorectal cancer cells." (PMID 27145365, 2016).
colorectal cancer (continued). "It was shown that PrPC silencing reduced the metastatic potential of CSCs sorted from human colorectal cancers as CD44+, a stem-like membrane receptor involved in cell adhesion, motility, and metastasis." (PMID 27229535, 2016). "In colorectal cancer, specific CD44 isoforms are expressed according to the progression of the disease." (PMID 25904917, 2015). "Recently, CD44 has been extensively used as a surface marker to isolate cancer stem cells (CSCs) from breast, prostate, pancreas, ovarian and colorectal cancers." (PMID 25909162, 2015). "CD44-positive cells promote tumorigenesis in breast and colorectal cancers, displaying stem cell properties, such as self-renewal and differentiation." (PMID 25909162, 2015). "Radiation itself has also been shown to increase the expression of AKT, CD133, and reduce the expression of CD44 in colorectal cancer cells." (PMID 24760019, 2014). "Among them, CD44 was also found be abnormally spliced in colorectal cancer and was suggested to be the character of metastatically potent tumor cells." (PMID 25499959, 2014). "In contrast, raft affiliation of CD44 has been demonstrated to recruit Src and integrins in gastric and colorectal cancers, promoting cell survival and increasing endothelial adhesion." (PMID 24512624, 2014). "This was recently pinpointed in a study using material from colorectal cancer patients, which showed that a combined expression of high CD133/CD44 was useful to identify putative colorectal cancer stem cells and tumors with a poor prognosis." (PMID 24760019, 2014). "In contrast CD44+ stem-like cells, isolated from colorectal cancer cell line, displayed reduced topo I activity and insensitivity of the enzyme to camptothecin, compared to the CD44− subpopulation." (PMID 25472619, 2014). "Since the EpCAMhigh/CD44+ phenotype of colorectal cancer cells, which has stem cell-like properties, was confirmed, it has been regarded as an effective marker of colorectal cancer stem cells." (PMID 24765173, 2014). "The CD44+ and CD44− subpopulations of the colorectal cancer cell line Caco2 were analyzed separately for their sensitivities to the antitumor drug camptothecin." (PMID 24960044, 2014). "Nodal transcript and protein were hardly detectable in CD44- or CD24-negative human colorectal cancer cell lines, whereas Nodal and its receptors were present in CCSCs." (PMID 24696849, 2014). "Both CD24 and CD44 have been reported as putative markers for isolating colorectal cancer—initiating cells or CCSCs." (PMID 24696849, 2014). "Double immunohistochemical staining was used to detect the expression of EpCAM/CD44 in 80 cases of colorectal cancer and their corresponding liver metastases." (PMID 24765173, 2014). "The expression of EpCAM/CD44 in colorectal cancer was analyzed, and the correlation of EpCAMhigh/CD44+ with the biological behavior of colorectal cancer was explored." (PMID 24765173, 2014). "The aim of the present study was to explore the prevalence and clinical significance of colorectal cancer stem cell marker EpCAMhigh/CD44+ in colorectal cancer." (PMID 24765173, 2014). "CD44 marks stem cell-like cells in a number of tumour types, including colorectal cancer (CRC), while aberrant CD44 expression conveys increased tumourigenic, invasive, and metastatic potential." (PMID 24009708, 2013). "Although already reported as a predictive factor for recurrence in colorectal cancer patients, substantial controversy exists about the actual impact of different levels of CD44 gene expression." (PMID 24023782, 2013). "In 2007, reports were published on stem cells for colorectal cancer, and CD44 was identified as a cancer stem cell marker." (PMID 23800986, 2013). "We found that CD44 VE expression and metastasis formation showed inverse correlation, similarly to our recent findings in colorectal carcinomas." (PMID 23342032, 2013).
colorectal cancer (continued). "But very recently, and for the first time, a study in colorectal cancer revealed coexistence of CD133+ CD44+ stem-like cells with CD133+CD44high subset that exhibited more invasive in vitro and metastasis to liver in vivo." (PMID 22693526, 2012). "We managed to present a colorectal cancer-specific CD44 ASP, which remained unchanged from cell lines throughout primary tumour formation and metastatic progression." (PMID 23151220, 2012). "Our aim was to identify a roster of CD44 isoforms expressed by colorectal cancer to see the extent of complexity we need to face when examining ‘CD44’." (PMID 23151220, 2012). "As few as 100 cells, CD44+cells promoted tumourigenesis in breast, and colorectal cancer displaying stem cell properties such as self-renewal and differentiation." (PMID 22693526, 2012). "Recently, CD44 has also been reported to be a possible cancer stem cell marker for breast, pancreas, or colorectal cancer." (PMID 21819617, 2011). "To address this issue in a controlled ‘in vitro’ model, we investigated the invasive potential of CD44+/CD166+ or CD44−/CD166− cells derived from the human colorectal cancer cell lines, LS180, SW480, and Colo205." (PMID 20606680, 2010). "In some tumors, isolation of cells positive for CD166, in addition to ESA and CD44, further enriches for colorectal cancer stem cells (CoCSC), allowing for efficient tumorigenesis with as few as 200 ESA+CD44+CD166+ cells." (PMID 18560594, 2008). "Among the most interesting findings, surface antigen CD44, complement resistance factor CD55/Daf, and secreted phosphoglycoprotein OPN, all of which are known to be implicated in colorectal cancer, were also up-regulated by caMEK." (PMID 17112382, 2006). "In human, high CD44 expression was shown to correlate with tumour dissemination and poor prognosis in diffuse large cell lymphoma and in colorectal carcinoma." (PMID 15870832, 2005). "Based on the important role of CD44 in tumour progression and metastasis, we evaluated, in a prospective study, plasma-soluble CD44 (sCD44) as a serum marker in colorectal cancer." (PMID 10471052, 1999). "In the development of CD44‐targeted antitumor strategy, doxorubicin modified with anti‐CD44mAb exhibited pronounced increase in cellular uptake and elevated intracellular doxorubicin concentration than doxorubicin in CD44‐positive colorectal cancer model." (PMID 41346572, 2025). "Notably, the combination of stemness inhibitors reduced stemness markers (CD133, CD44) in colorectal cancer cells and shifted macrophage polarization toward an M1-like phenotype, particularly in co-culture with HCT116." (PMID 40160820, 2025). "Furthermore, overexpression of CD44 isoforms containing CD44v6 (CD44v6-overexpressing cells) demonstrated an increase in resistance to 5-FU in colorectal cancer cells." (PMID 40114966, 2025). "CD44 has the function of maintaining the activity of colorectal cancer stem cells." (PMID 41225509, 2025). "In colorectal cancer, EphA2 and EphB2, belonging to the tyrosine kinase receptor family, have been identified as novel markers for colorectal CSCs, whose expression is strongly correlated with the expression of CD44 and Lgr5, as well as the stemness of colorectal cancer cells." (PMID 41346572, 2025). "Notably, both dimers suppressed the growth of the CD44+ colorectal cancer stem cell line P6C, with IC50 values of 16.48 and 34.76 μM, respectively." (PMID 41515395, 2025). "According to recent research, β-carotene decreased the number of colonospheres in CD133+/CD44+ colorectal cancer cells through (i) the up-regulation of histone H3/4 acetylation, (ii) the down-regulation of DNA methylation, and (iii) decreased oncogenic miRNA-1260b and miRNA-296-3p." (PMID 39859345, 2025). "FGB was shown to interact with CD44 to participate in hematogenous metastasis in colorectal cancer." (PMID 39227068, 2024). "Pan‐CD44 knockdown decreases spontaneous metastasis in human colorectal cancer xenograft models." (PMID 37849446, 2024).
colorectal cancer (continued). "CD44 is widely expressed in tumor cells and plays a critical role in various aspects of colorectal cancer (CRC) development and progression, including tumorigenesis, progression, epithelial-mesenchymal transition (EMT), metastasis, and resistance to apoptosis, chemotherapies, and radiotherapies." (PMID 38167453, 2024). "Additionally, another research also suggested that NaB promoted ferroptosis in colorectal cancer cells through the CD44/SLC7A11 pathway." (PMID 38397738, 2024). "Besides, TNFAIP6 facilitates aggressiveness in a CD44-dependent manner to enhance metastasis in colorectal cancer." (PMID 38376551, 2024). "Some function of TSG-6 may be related to its competitive binding to CD44 with TLR; it enhances the invasiveness of colorectal cancer cells in a CD44-dependent manner and creates a favourable microenvironment for metastasis by reprogramming normal fibroblasts." (PMID 38791985, 2024). "In colorectal cancer, hsa-miR-6511b-5p could inhibit cancer cell migration and invasion through methylation of CD44 by targeting BRG1." (PMID 39135979, 2024). "In addition, overexpression of CD44 restores the cell proliferation suppressed by BNIPL‐2 and BNIPL-2, which can promote migration, invasion, and metastasis of colorectal cancer cells via CD44." (PMID 38302910, 2024). "Colorectal cancer stem cells exhibit enhanced CD44, CD133 and Lgr5 expression; therefore, loss of Fzd7 may initiate tumorigenesis in the colon." (PMID 36691900, 2023). "Also, our PubMed search shows that there are 1,104 published papers on CD44 and colorectal cancer (CRC)." (PMID 37005380, 2023). "CD44 was considered to promote stemness and invasiveness in colorectal cancer." (PMID 37228620, 2023). "CD133 and CD44 are the most frequently reported CSC markers for colorectal cancer." (PMID 37639070, 2023). "The relevance of the knockout of Cd44 in the intestinal epithelium upon the requirement of augmented Wnt activity, having only a mild phenotype in homeostatic conditions depicts the potential of CD44 as a therapeutic target in pathologically augmented Wnt signaling, as in colorectal cancer." (PMID 35190527, 2022). "Subsequently, we explored whether miR-6511b-5p influenced colorectal cancer metastasis in a CD44-dependent manner in SW620 and HT29 cells." (PMID 35590122, 2022). "In conclusion, CD44-shRNA adenovirus might affect colorectal cancer cells and induce apoptosis among cancerous cells by attacking CD44." (PMID 36415383, 2022). "This research discovered the up-regulation of LINC01315 in CD133+/CD44+ colorectal cancer stem cells for the first time, indicating that LINC01315 might be associated with the stemness of colorectal cancer cells." (PMID 35470736, 2022). "Exosomes derived from CD133+/CD44+ colorectal cancer stem cells were collected." (PMID 35470736, 2022). "CD44 plays a pivotal role through tumorigenesis by regulating cancer cell metastasis, stemness, and chemosensitivity and is considered a promising therapeutic target for human cancers, including colorectal cancer (CRC)." (PMID 37646068, 2022). "However, the effects of CD44 silencing on biological behaviors of CSCs remain to be investigated in colorectal cancer." (PMID 35229451, 2022). "Furthermore, BRG1 knockdown decreased the expression of CD44 by promoting CD44 methylation in colorectal cancer cells." (PMID 35590122, 2022). "In addition, we demonstrated that the expression of BRG1 and CD44 were both upregulated in pMMR colorectal cancer tissues and downregulated in dMMR samples by RT-qPCR and western blot analysis." (PMID 35590122, 2022). "Our findings confirm that targeting colorectal CSCs is a promising therapy for colorectal cancer, and CD44 may be a novel therapeutic target for the treatment of colorectal cancer." (PMID 35229451, 2022).
colorectal cancer (continued). "Our assumption that exosomes containing LINC01315 secreted by CD133+/CD44+ colorectal cancer stem cells could promote the malignant behaviors of colorectal cancer cells to enhance the development of colorectal cancer was confirmed." (PMID 35470736, 2022). "First, we examined whether the CD44 promoter is hypermethylated in BRG1 knocked down colorectal cancer cell lines." (PMID 35590122, 2022). "Finally, we elucidated the mechanism by which miR-6511b-5p inhibits the migration and invasion of MSS colorectal cancer cells via the BRG1/CD44 axis." (PMID 35590122, 2022). "In our research, LINC01315 silencing was proved to inhibit the viability as well as the abilities of proliferation, sphere formation, and migration of CD133+/CD44+ colorectal cancer stem cells, demonstrating that LINC01315 played an important role in the stemness of colorectal cancer cells." (PMID 35470736, 2022). "For example, lncRNA LOC100507144 could contribute to colorectal cancer progression and metastasis through regulating CD44/Nanog/Sox2/miR-302/miR-21 axis." (PMID 35635595, 2022). "CD44 has shown prognostic values and promising therapeutic potential in multiple human cancers; however, the effects of CD44 silencing on biological behaviors of cancer stem cells (CSCs) have not been fully understood in colorectal cancer." (PMID 35229451, 2022). "Finally, real-time quantitative PCR, immunohistochemistry, and chromatin immunoprecipitation (ChIP) assays were performed to analyze the relationship between BRG1 and CD44 in colorectal cancer." (PMID 35590122, 2022). "Thereafter, ChIP assays were performed to validate whether BRG1 interacts directly with the CD44 promoter in colorectal cancer cells." (PMID 35590122, 2022). "Nonetheless, whether BRG1 promotes the expression of CD44 by demethylating the promoter of the CD44 gene in colorectal cancer requires further study." (PMID 35590122, 2022). "The HOTAIR/miR-326 axis was shown to regulate FUT6 expression to promote fucosylation of CD44 in colorectal cancer, and fucosylated CD44 could activate the PI3K/AKT/mTOR pathway to promote tumor progression." (PMID 35936713, 2022). "CD133+/CD44+ colorectal cancer stem cells were sorted and verified through flow cytometry." (PMID 35470736, 2022). "We further determined whether the expression of either CD44 or SOX2 in response to radiation is dependent on radioresistant colorectal cancer cells." (PMID 33445526, 2021). "Similar findings have been observed with CD133 mRNA-loaded DC vaccination in humanized glioma models, CD44-loaded DCs in colorectal cancer, and different other approaches that might be based on DCs, T cells, and oncolytic viruses." (PMID 33498502, 2021). "Furthermore, the overexpression of the UTR of EMT genes increased the expression of CD44, a marker of colorectal cancer stem cells, as well as therapeutic resistance against paclitaxel." (PMID 34502497, 2021). "HNRNPLL regulates AS of CD44 to promote proliferation and metastasis of colorectal cancer." (PMID 33976726, 2021). "Comparable to the results found in mice, CD44 is overexpressed in human colorectal cancer." (PMID 33532580, 2021). "Notably, the biological role and characteristics of the CD44+CD133+ subpopulation in human colorectal cancer remain incompletely understood." (PMID 33994850, 2021). "Interestingly, the induction of SOX2 and CSC characteristics, including CD44+ cells in colorectal cancer, were only affected by the inactivation and downregulation of PI3K/AKT following irradiation." (PMID 33445526, 2021). "Our data indicate that loss of PCGF1 decreases H3K4me3 and increases H3K27me3 at the promoters of stemness markers, suggesting that PCGF1 activates the stemness markers CD133 and CD44 through the H3K4me3 and H3K27me3 modifications in the promoter region of colorectal cancer stem cells." (PMID 34148069, 2021).